CASR (calcium sensing receptor)
Diseases named in the same sentence as CASR in open-access papers (continued):
Sharing a sentence is not in itself a finding about the gene and the disease.
Hypercalcemia (continued). "The independent effect of hypercalcemia on cancer development and prognosis is widely investigated in colorectal-, and breast cancers; however, it still remained undetermined whether the functional status of CaSR could be related to cancer outcomes in affected patients." (PMID 33528764, 2021). "Moreover, our results are the first to report that an AP2σ mutation (Met117Ile) that does not involve the Arg15 residue can impair CaSR-mediated signalling, and may be associated with hypercalcaemia, consistent with FHH3." (PMID 29325022, 2018). "By acting through the calcium-sensing receptor, hypercalcemia can lead to negative feedback on 25-hydroxyvitamin D 1α-hydroxylase activity." (PMID 39574220, 2025). "It is therefore possible that some cats with hypercalcemia have unidentified CaSR SNPs that account for the lack of calcitonin response in the face of hypercalcemia." (PMID 38887540, 2024). "Activation of CaSR interferes with NKCC2, similar to furosemide, and inhibits vasopressin-mediated traffic of aquaporin-containing vesicles, explaining the diuretic actions of hypercalcemia in multiple species." (PMID 34181644, 2021). "According to this effect, CaSR activation in hypercalcemic conditions would facilitate the NKCC2 function, thereby increasing the driving force for paracellular reabsorption of divalent cations and aggravating hypercalcemia." (PMID 32659887, 2020). "Heterozygous inactivating mutations in the calcium-sensing receptor (CaSR) gene are known to cause familial hypocalciuric hypercalcemia (FHH), usually a benign form of hypercalcemia without symptoms of a disrupted calcium homeostasis." (PMID 30895164, 2019). "We describe a 65‐year‐old woman who had hypercalcemia with normal circulating parathyroid hormone concentrations and hypocalciuria, features consistent with FHH, but she did not have CaSR and AP2σ mutations." (PMID 26729423, 2016). "Whether the consequence of CaSR activation, or influx via VGCC, ultimately increases in [Ca2+]i are likely to provide the underpinning stimulus for the suppressive effects of fetal hypercalcemia on branching morphogenesis." (PMID 24282533, 2013). "Mice with homozygous deletion of the calcium-sensing receptor (CaR) mimic the syndrome of neonatal severe hyperparathyroidism (NSHPT) in humans with very high circulating parathyroid hormone (PTH) and severe life-threatening hypercalcemia." (PMID 21966280, 2011). "Cinacalcet helps to manage hypercalcemia caused by PC by suppressing PTH secretion; however, its effectiveness may be limited in advanced tumors that do not express the calcium-sensing receptor." (PMID 40806850, 2025). "The presence of CaSR SNPs could also explain the disparity in the number of calcitonin-positive C cells between responders and non-responders to experimental hypercalcemia." (PMID 38887540, 2024). "The hypoactivity of calcium-sensing receptor (CaSR) facilitates calcium (Ca2+) renal absorption and parathormone (PTH) production despite mildly elevated serum Ca2+ levels, resulting in different degrees of hypercalcemia, hypocalciuria and inappropriately elevated PTH." (PMID 38214877, 2024). "This notwithstanding, as cancer progresses to the more malignant stages, patients inevitably develop cancer-induced hypercalcemia which may invariably influence the progression of the disease via the CaSR or independent of CaSR." (PMID 35355564, 2022). "CaSR may reside both in the apical and basolateral membranes of DCT cells and effects of plasma- vs. urinary Ca2+ on NCC may be different, i.e., inhibition by hypercalcemia vs. stimulation in hypercalciuric conditions." (PMID 32659887, 2020). "Together, these results suggest that physiological fetal hypercalcemia stimulates fluid secretion via the CaSR in the developing human lung, a process which does not occur in the developing mouse lung, where hypercalcaemia drives anion-driven fluid secretion through channels other than CFTR." (PMID 26911344, 2016).
Hypercalcemia (continued). "The resulting hypercalcemia would normally inhibit osteoclast activity, however, due to the LOF in the CaSR-pathway in osteoclasts, this mechanism does not work properly." (PMID 35566721, 2022). "However, in PHPT due to depressed CaSR expression onset, the feedback mechanism between calcium and PTH is disrupted so that hypercalcemia fails to block PTH secretion, thereby aggravating the PHPT symptoms." (PMID 36755240, 2023).
Hypocalcemia (83 papers, 2007 to 2025). An abnormally decreased calcium concentration in the blood. "Studies have shown that single nucleotide polymorphisms (SNPs) of CASR alter the response to calcified cinnacalcium and help in the treatment of hypocalcemia in CKD hemodialysis patients." (PMID 41208959, 2025). "To evaluate the efficacy of AXT914 for ADH1, we undertook in vitro and in vivo studies involving the nuclear flecks (Nuf) mouse model, which has hypocalcemia in association with a germline gain-of-function CaSR mutation, Leu723Gln." (PMID 40086735, 2025). "(ii) Use biomarkers with diagnostic and prognostic leverage: 21-hydroxylase for AAD; neutralizing anti-IFN for APS-1; anti-CaSR for unexplained hypocalcemia; DNAm signatures for risk stratification in AITD (pending validation)." (PMID 41465179, 2025). "Gain‐of‐function mutations in the calcium‐sensing receptor (CaSR) are linked to hypocalcemia and hypomagnesemia development." (PMID 40893394, 2025). "The autosomal dominant hypocalcemia hypercalciuria (type V) results from a gain-of-function mutation in the gene encoding calcium-sensing receptor (CaSR); hypocalcemia and hypomagnesemia are prevalent in this type." (PMID 40666068, 2025). "In light of hypocalcemia in COVID-19 patients and its association with hypoparathyroidism, we detected significant levels of the anti-CaSR antibody (calcium receptor) in LC cohort." (PMID 38304426, 2024). "FIH can also be caused by an activating pathogenic variant in the calcium sensing receptor (CASR); inappropriate activation of this sensor signals Ca sufficiency even during hypocalcemia, thereby suppressing PTH secretion." (PMID 39439810, 2024). "In light of hypocalcemia in COVID-19 patients and its association with hypoparathyroidism, we detected significant levels of the anti-CaSR antibody in our LC cohort." (PMID 38304426, 2024). "We applied machine learning methods to differentiate between mutations that cause either a gain or loss of function in CaSR, leading to disorders like hypercalcemia and hypocalcemia." (PMID 39531485, 2024). "For example, cinacalcet is a calcium-sensing receptor agonist used to treat secondary hyperparathyroidism; occasionally, cinacalcet can cause hypocalcemia in a dose-dependent manner." (PMID 38700923, 2024). "We present the case of a female newborn with genetic hypoparathyroidism (L125P mutation of CASR gene), hypocalcemia, and neonatal seizures due to the potential correlation between refractory neonatal seizures and ADH1." (PMID 37371242, 2023). "Considering ICI, nivolumab and ipilimumab, which can be used in association in a combination strategy, are associated with an increased risk of hypocalcemia, mediated by an autoimmune mechanism targeted on the calcium-sensing receptor." (PMID 36672478, 2023). "We report a novel heterozygous mutation (c.416T>C) in CASR that caused ADH1 in all seven family members with hypocalcemia." (PMID 36812896, 2023). "Both are disease-associated mutations in humans that result in loss-of-function (for R227L) or gain-of-function (for E228K) in CaSR and cause hyperparathyroidism and hypocalcemia, respectively." (PMID 35459864, 2022). "Hypocalcemia mediated by vitamin D deficiency can intensify the sensitivity of the parathyroid glands to vitamin D by reducing CaSR expression." (PMID 36015101, 2022). "Clinically this presents as hypocalcaemia associated with an inappropriately normal-high urinary calcium excretion, presumably due to increased activity of the CaSR in the kidney." (PMID 33614549, 2021). "Calcilytics have the potential to treat autosomal dominant hypocalcemia type 1 (ADH1), which is caused by germline gain‐of‐function CaSR mutations and leads to symptomatic hypocalcemia, inappropriately low PTH concentrations, and hypercalciuria." (PMID 33103030, 2020).
Hypocalcemia (continued). "ADH1 (OMIM #601198) has been reported in association with >70 different CaSR mutations, and is characterized by hypocalcemia, hyperphosphatemia, hypomagnesemia, inappropriately low or normal PTH concentrations, and a relative or absolute hypercalciuria." (PMID 31820785, 2020). "The aim of this study was to further investigate NPSP795 for the treatment of ADH1 by undertaking in vitro and in vivo studies involving Nuf mice, which have hypocalcemia in association with a gain‐of‐function CaSR mutation, Leu723Gln." (PMID 33103030, 2020). "As NPSP795 rectified the altered signaling responses associated with the Nuf mouse CaSR mutation (Leu723Gln) in vitro, we pursued studies to determine the effects of this calcilytic in Nuf mice, which have hypocalcemia and reduced plasma PTH concentrations." (PMID 33103030, 2020). "Because of the clinical findings, calcium-sensing receptor gene (CASR)-associated hypocalcemia (OMIM#601198) was initially suspected in the family." (PMID 31660939, 2019). "Another well-known source of hypocalcemia with low PTH levels is autosomal dominant hypocalcemia (ADH) triggered by an activating mutation in the genes encoding the calcium-sensing receptor (CaSR) mainly placed in the parathyroid glands." (PMID 29971010, 2018). "Hypocalcaemia, which is more rare, is related to heterozygous activating mutations of CASR, corresponding to autosomal dominant hypocalcaemia, sometimes with a presentation of pseudo-Bartter’s syndrome." (PMID 28122587, 2017). "Gain-of-function mutations in the gene encoding the calcium sensing receptor CaSR (CASR) are associated with hypercalciuric hypocalcemia and occasionally with hypomagnesemia." (PMID 27234911, 2017). "In theory, osteoblastic lesion in skeletal sites of metastatic prostate cancer causes hypocalcemia that in turn leads to calcium-sensing receptor (CaSR) activation, resulting in increased PTH production and secretion." (PMID 19602280, 2009). "Furthermore, in murine models of hypocalcemia induced by dietary calcium deficiency, inhibition of the calcium-sensing receptor (CaSR) signaling pathway alleviates its suppressive effect on PTHrP secretion, resulting in elevated circulating levels of PTHrP." (PMID 40860924, 2025). "Furthermore, human genetic mutations deleting these bridges and associated with hypocalcemia result in elevated CaSR constitutive activity." (PMID 38664468, 2024). "However, parathyroid hyperplasia was not caused by enhanced intracellular accumulation of the mutant pro[P1]PTH, as in dominant variants of hypoparathyroidism but because of hypocalcemia and consequently insufficient activation of the CaSR." (PMID 36795755, 2023). "Further studies in larger groups of patients with various CASR mutations are needed to examine the effect of implementing our paradigm for the prevention of both hypocalcemia-related neurological symptoms and hypercalciuria with subsequent renal impairment in patients with ADH1." (PMID 36812896, 2023). "Mutations in CASR result in distinct phenotypes causing either hyper- or hypocalcaemia." (PMID 33614549, 2021). "A Bartter-like phenotype of these CASR activating mutations results in a presentation of hypokalemic metabolic alkalosis, with moderate secondary hyperaldosteronism without very severe salt loss, but with a tendancy for hypercalciuric hypocalcemia." (PMID 28122587, 2017). "Therefore, the mechanism of hypocalcemia appears similar to that of activating mutations in the CASR, namely an increase in the sensitivity of parathyroid cells to extracellular ionized calcium." (PMID 27803672, 2016). "Autosomal dominant hypocalcemia type 1 (ADH1) is caused by germline gain-of-function mutations of the calcium-sensing receptor (CaSR) and may lead to symptomatic hypocalcemia, inappropriately low serum PTH concentrations and hypercalciuria." (PMID 26052899, 2015).
Hypocalcemia (continued). "The hypocalcemia exhibited by two of the siblings together with a BS phenotype suggested that a CASR mutation may be the underlying cause." (PMID 24400161, 2013). "Activating mutations of the CASR gene give rise to hypercalciuria and hypocalcemia because of the direct effect in TALH cells (where the CaSR can inhibit calcium absorption) and to the inhibition of PTH secretion, which induces additional downregulation of calcium absorption in the distal tubule." (PMID 17464515, 2007). "A subgroup of CASR gain-of-function variants leads to renal loss of sodium, chloride and magnesium resulting in hyperreninemia, hyperaldosteronism with normal blood pressure, hypokalemia and metabolic alkalosis, in addition to hypocalcemia and relative hypercalciuria." (PMID 39607645, 2025). "Several other authors reported hypocalcemia secondary to ICI treatment related to a possible autoimmune mechanism that can be caused by either immune-mediated destruction or by the hyperactivation of the CaSR by activating autoantibodies, as previously reported." (PMID 36672478, 2023). "With respect to salt-handling, global effects of CaSR hyperactivity due to gain-of-function mutations in the human CaSR gene recapitulate a Bartter-like syndrome with moderate salt wasting but rather severe hypocalcemia compared to the classical Bartter syndrome variants." (PMID 32659887, 2020). "Autosomal Dominant Hypocalcemia type 1 (ADH1), caused by gain-of-function variants in the calcium-sensing receptor (CASR), is characterized by a variable degree of hypocalcemia and hypercalciuria with inappropriately low PTH." (PMID 39607645, 2025). "In mice with diet-induced hypocalcemia, the inhibition of the CaSR signaling pathway alleviates its suppressive effect on PTHrP secretion, promoting PTHrP production and release." (PMID 40860924, 2025). "First, mutations in calcium-sensing receptors (CASR) can suppress PTH levels and exert a hypercalciuric hypocalcemia condition." (PMID 40000975, 2025). "This suggests a compensatory hormonal response despite mild hypocalcemia, and highlights incomplete penetrance in autosomal dominant hypocalcemia type 1 (ADH1) due to a CASR mutation." (PMID 41155848, 2025). "Autoantibodies against CaSR can act as functional receptor agonists, directly inhibiting PTH secretion and causing hypocalcemia." (PMID 41465179, 2025). "Gain-of-function mutations in the TM6–TM7 transmembrane region of CASR drive ADH1 by increasing receptor sensitivity to calcium, lowering the PTH suppression threshold, and causing hypocalcemia with low PTH and hypercalciuria." (PMID 41155848, 2025). "During hypocalcemia, CaSR is inactivated, which stimulates PTH secretion and subsequently the synthesis of calcitriol in the kidneys by the enzyme 1α-hydroxylase, regulated by the CYP27B1 gene." (PMID 38613476, 2024). "AD hypocalcemia/AD hypocalcemia with Bartter syndrome (OMIM phenotype number 601198) is a condition resulting from activating variants in CASR, which increase the sensitivity of CaSR to extracellular calcium." (PMID 38606357, 2024). "Hypocalcemia is also known to stimulate the Ca and P intestinal absorption through the inhibition of the CaSR, leading to increased PTH secretion." (PMID 38613476, 2024). "The activation of CaSR by autoantibodies cause reduced PTH secretion and hypocalcemia, with similar mechanisms reported for the calcimimetic drug cinacalcet." (PMID 36672478, 2023). "Based on this assumption, viral-induced CaSR over-expression would render parathyroid glands hypofunctional, causing PTH impairment and hypocalcemia; nevertheless, studies on this regard are still missing." (PMID 36467702, 2022). "The clinical use of cinacalcet in hyperparathyroidism has been limited by its propensity to induce hypocalcemia, in part due to activation of CaSR in the thyroid gland and stimulation of calcitonin release." (PMID 36267284, 2022).
Hypocalcemia (continued). "Because of this, the CaSR has been addressed as a key factor responsible for hypocalcemia and low levels of PTH that are commonly found in critically ill patients under sepsis or after burn injury." (PMID 36467702, 2022). "IL‐1 and IL‐6 activation of parathyroid and renal CaSR results in hypocalcemia, hypovitaminosis D, and hypoparathyroidism." (PMID 35894711, 2022). "The calcium-sensing receptors (CaSR) on the surface of chief cells in PTGs are sensitive to variation of serum calcium, that is how hypocalcemia leads to hypersecretion of iPTH." (PMID 35164637, 2022). "A decrease in serum ionized Ca+2 (hypocalcemia) inactivates the CaSR in the parathyroid glands and subsequently stimulates PTH secretion." (PMID 33542868, 2021). "Various mutations in the CASR gene leading to diseases such as familial hypocalciuric hypercalcemia (FHH; loss-of-function mutation) or hypocalcemia (gain-of-function mutation) have been described." (PMID 34444650, 2021). "Activating CaSR mutations cause autosomal dominant hypocalcaemia type-1 (ADH1), characterised by mild-to-moderate hypocalcaemia, with inappropriately low-to-normal serum PTH." (PMID 34077389, 2021). "CASR encodes the calcium-sensing receptor (CaSR), responsible for increasing secretion of PTH during hypocalcemia." (PMID 32986719, 2020). "In previous reports, hypocalcemia, caused by hyperphosphatemia and reduced 1,25(OH)2D in CKD, inactivated CaSR in PTGs and increased PTH secretion." (PMID 32517664, 2020). "PTH is an 84-amino acid polypeptide secreted in response to hypocalcemia via calcium-sensing receptors (CaSR) present on the surface of the parathyroid glands." (PMID 32823917, 2020). "These patients express activating mutations in CaSR, or in G protein 11 (GNA11), which cause hypocalcemia, inappropriately low PTH levels, and moderate hyperphosphatemia." (PMID 31619668, 2019). "To do so, we performed a literature review with the keywords calcium-sensing receptor, hypocalciuric hypercalcaemia, hypocalcemia and hyperparathyroidism." (PMID 28122587, 2017). "Our study has revealed Dsk7 mice to have hypocalcemia and reduced PTH concentrations, which are caused by a gain-of-function Gna11 mutation that leads to upregulation of CaSR-mediated Ca2+i and MAPK signaling responses." (PMID 28194447, 2017). "In the kidneys, CaSR stimulates Ca2+ reabsorption in the cortical thick ascending limb in response to hypocalcemia, and 1-hydroxylation of 25-hydroxyvitamin D3 [25(OH)D3] in the proximal renal tubules." (PMID 28690912, 2017). "Increased PTH secretion in response to hypocalcemia is mediated by the calcium-sensing receptor (CaSR) a G-protein coupled receptor (GPCR) located on the parathyroid glands." (PMID 24884838, 2014). "Gain-of-function mutations of the calcium-sensing receptor (CaSR) result in autosomal dominant hypocalcemia type 1 (ADH1), which may cause symptomatic hypocalcemia with low parathyroid hormone concentrations." (PMID 40086735, 2025). "The dysfunction of the parathyroid glands leads to hypocalcemia and hyperphosphatemia, with low parathyroid hormone levels in the presence of antibodies against parathyroid autoantigens, such as the calcium-sensing receptor, NACHT leucine-rich repeat protein 5, NALP5, or organ-specific antibodies." (PMID 38673639, 2024). "However, clinical use of CIN is limited because it induces clinically significant hypocalcemia, likely resulting from both suppressed renal calcium reabsorption and calcitonin-mediated inhibition of bone resorption via CaSR activation in thyroid C-cells." (PMID 35457141, 2022). "A novel heterozygous p.Ser448Pro CaSR variant was identified in the hypercalcemic individuals, but not the children with hypocalcemia or normocalcemia." (PMID 32150253, 2020).